TPM4 (tropomyosin 4)
Diseases named in the same sentence as TPM4 in open-access papers (continued):
Sharing a sentence is not in itself a finding about the gene and the disease.
glioma (continued). "A total of 95 overlapping TPM4-correlated genes were screened out, and they were shown to be mainly correlated with biological adhesion, cell adhesion, cell motion, and extracellular matrix/structure organization, which were similar to those in pan-gliomas." (PMID 36138856, 2022). "Moreover, upregulation of TPM4 predicted significantly worse survival for glioma patients across different WHO grades." (PMID 36138856, 2022). "The results above indicated that TPM3 and TPM4 could serve as disadvantageous factors for the survival of glioma, while TPM3 served as an independent predictor of a bad prognosis." (PMID 35892971, 2022). "IDH-wildtype and mesenchymal subtype gliomas were accompanied by TPM4 upregulation." (PMID 36138856, 2022). "Taken together, TPM4 may be a useful biomarker for predicting OS in glioma patients." (PMID 36639743, 2023). "Assessment of the prognostic value of TPM4 expression in glioma patients subgrouped by histological type, sex, IDH mutation status, WHO grade, chromosome 1p/19q codeletion, and patient age showed that high expression of TPM4 was associated with poorer prognosis in all of these groups." (PMID 36639743, 2023). "These research findings strongly demonstrate that TPM4 may be a prognostic biomarker for glioma." (PMID 36639743, 2023). "Therefore, we focused on TPM4 to search for a new biomarker of glioma." (PMID 36138856, 2022). "Thus, TPM4 was considered to be potentially involved in the EMT development in gliomas." (PMID 36138856, 2022). "In addition, we used WHO grade, chromosome 1p/19q codeletion, primary therapy outcome, IDH status, and TPM4 levels as indicators to construct a prognostic nomogram, which can be employed by physicians to enhance the accuracy of the clinical identification of glioma patients." (PMID 36639743, 2023). "However, the clinical significance and expression profile of TPM4 in glioma remains unclear." (PMID 36138856, 2022). "This study comprehensively analyzed the expression patterns of TPM4 at the transcriptional level and its clinical characterization in whole WHO grade of gliomas based on 998 glioma patients." (PMID 36138856, 2022). "Additionally, TPM4, the suppression of which can inhibit metastasis in in hepatocellular carcinoma (HCC), showed significantly higher levels in glioma than in healthy brain tissue, which correlated with poor prognosis of patients." (PMID 38607010, 2024). "Previous studies have shown that TPM4 is related to the development and progression of multiple cancers, but the study of TPM4 in glioma is not clear." (PMID 36639743, 2023). "The results indicated that TPMs, especially TPM3 and TPM4, may function as oncogenes, and a high expression of TPM3/4 could be correlated to a worse prognosis outcome in glioma." (PMID 35892971, 2022). "The results showed that TPM2, TPM3, and TPM4 were more expressed in high-grade gliomas than in low-grade gliomas, while for TPM1, the trend was not as evident as in other groups." (PMID 35892971, 2022). "Furthermore, GSEA analysis revealed a robust relationship between TPM4 and EMT phenotype, which had been identified as a vital process in tumor migration, invasion, recurrence, and therapeutic resistance in glioma cells." (PMID 36138856, 2022). "We found that the expression of TPM4 in gliomas positively correlated with the infiltration of various immune cells, such as T cells, Th2 cells, macrophages, and neutrophils, while it negatively correlated with the infiltration of CD8 T cells and pDCs in glioma." (PMID 36639743, 2023). "Currently, there is a lack of knowledge on the role of TPM4 in glioma." (PMID 36138856, 2022). "However, studies on TPM4 in glioma patients are currently lacking." (PMID 36639743, 2023).
colon carcinoma (7 papers, 2019 to 2023). "Compared with normal colon tissues and colonic epithelial cell lines, the mRNA and protein expression of TPM4 in colon cancer tissues were decreased, respectively." (PMID 37686101, 2023). "In a study of colon cancer, TPM4 expression was shown to be reduced in colon cancer tissues and cell lines." (PMID 37686101, 2023). "TPM4 was found to be abnormally expressed in a variety of cancers, and it was considered to be a potential biomarker for liver cancer, ovarian cancer, colon cancer, etc.." (PMID 37328795, 2023). "On the contrary, in uterine cervix cancer and colon cancer, higher TPM4 predicted a better prognosis." (PMID 36138856, 2022). "Further investigations showed a role of TPM4 in cancer physiology, specifically, we found that miR-133a downregulation leads to TPM4 upregulation in colon carcinoma (CRC), and this correlates with a lower patient survival." (PMID 34575979, 2021). "Our results demonstrated that colon carcinoma patients showing higher TPM4 expression had a lower survival, as compared to those with lower TPM4 expression." (PMID 34575979, 2021). "In colon cancer the miR-133a-TPM4 axis is able to control cell migration and invasion by remodelling of the cytoskeleton." (PMID 34575979, 2021). "Our results identified TPM4 as a new candidate gene in the physiology of colon cancers, suggesting that the miR-133a-TPM4 axis plays a crucial role in tumour development." (PMID 34575979, 2021). "In addition, up-regulation of TPM4 expression can inhibit the expression of genes related to migration, invasion, and metastasis of colon cancer cells." (PMID 37686101, 2023). "In addition, cancers with abnormal TPM4 expression have been confirmed, including lung cancer, breast cancer, esophageal cancer, ovarian cancer, cervical cancer, prostate cancer, and colon cancer." (PMID 37686101, 2023). "Consistently, miR-133a results to be less expressed in colon cancer tissue rather than in the normal tissues, thus demonstrating the connection between the loss of miR-133a during tumour development, with the TPM4 upregulation." (PMID 34575979, 2021). "Furthermore, in colon cancer, high expression of TPM4 has been correlated with shorter overall survival, while we found that TPM4 hypermethylation was linked with transcriptional downregulation, as well as with BCR in PCa, together suggesting a cell type-specific role." (PMID 30866497, 2019).
hepatocellular carcinoma (7 papers, 2021 to 2024). A malignant tumor that arises from hepatocytes. "The LLPS of YBX1 enhanced by circASH2 promotes the decay of TPM4 transcripts, effectively inhibiting the metastasis of hepatocellular carcinoma by mediating cytoskeleton remodeling." (PMID 39749343, 2024). "Bioinformatics prediction and dual luciferase reporter gene assays proved that SOX9 and TPM4 were the target genes of miR-5195-3p in hepatoma cells." (PMID 37328795, 2023). "CircASH2 enhances the LLPS of nuclear Y-box binding protein 1 (YBX1) in hepatocellular carcinoma, and also enhances the attenuation of the primary target protein tropomyosin 4 (TPM4) transcripts, thereby altering the tumor cytoskeleton structure to inhibit HCC metastasis." (PMID 38546385, 2024). "Finally, a conclusion can be drawn from the experiment that TPM4 is highly expressed in hepatoma cells compared with normal hepatic tissues." (PMID 33390785, 2021).
inflammatory myofibroblastic tumor (6 papers, 2013 to 2022). A multinodular intermediate fibroblastic neoplasm that arises from soft tissue or viscera, in children and young adults. "Many translocations have been found with this ALK gene, including EML4:ALK which is responsible for approximately 3-5% of non-small-cell lung cancer(NSCLC), RANBP2:ALK, TPM4:ALK in inflammatory myofibroblastic tumor, NPM1:ALK, ATIC:ALK, TFG:ALK in anaplastic large cell lymphoma, and so on." (PMID 24564548, 2013). "Moreover, the RNA-seq results refined the consensus diagnosis in 5 (11%) additional patients, including SRF-NCOA1 in spindle cell rhabdomyosarcoma, MYOD1 p.L122R in sclerosing rhabdomyosarcoma, TPM4-ALK in inflammatory myofibroblastic tumor, and BCOR-CCNB3 in clear cell sarcoma of the kidney." (PMID 34131151, 2021). "In solid tumors, ALK rearrangements including TPM4-ALK and TPM3-ALK have been identified in up to 50-75% of inflammatory myofibroblastic tumors (IMT)." (PMID 35233056, 2022). "Another tropomyosin gene, TPM4, has also been found to be fused to the ALK gene in inflammatory myofibroblastic tumors (IMT) and other tumors." (PMID 25888090, 2015). "In a patient with an inflammatory myofibroblastic tumor, conventional fluorescence in situ hybridization (FISH) analysis showed negative ALK rearrangement, but a TPM4-ALK translocation was detected by targeted sequencing." (PMID 31747416, 2019).
ovarian carcinoma (6 papers, 2011 to 2023). A malignant neoplasm originating from the surface ovarian epithelium. "Similar to the downregulation of TPM4 gene expression in PCa found in the current study, TPM4 has previously been reported as downregulated in metastatic lung cancer, but as upregulated in ovarian cancer." (PMID 30866497, 2019). "Following treatment with platelet releasate, SK-OV-3 cells also showed expression changes in genes involved in, anti-autophagy in endometrial and ovarian cancer [KIAA1324/EIG121], as well as transcriptional regulation [ACTL6A], cell cycle[MUS81], cytoskeletal [TPM4] and homeostatic [TPM4] processes." (PMID 22022533, 2011).
cervical cancer (4 papers, 2022 to 2024). A primary or metastatic malignant neoplasm involving the cervix. "For instance, Aoran Luo demonstrated that PTBP1 interacted with lncRNA SFTA1P to regulate the degradation of TPM4 mRNA, thereby promoting the proliferation, migration, and invasion of cervical cancer cells." (PMID 38247832, 2024). "In the present study, we demonstrated that TPM4 knockdown can promote the proliferation and migration of cervical cancer cells, suggesting that TPM4 acts as a tumor suppressor in cervical cancer." (PMID 36344495, 2022). "CCK8 and colony formation indicated that TPM4 knockdown significantly promoted proliferation in cervical cancer cells." (PMID 36344495, 2022). "Results from transwell assays and wound healing also demonstrated that TPM4 knockdown promoted the migration and invasion of cervical cancer cells." (PMID 36344495, 2022). "Analysis of its mechanism revealed that lncRNA SFTA1P regulates cervical cancer progression by interacting with PTBP1 protein to facilitate TPM4 decay." (PMID 36344495, 2022). "Furthermore, through interactions with recombinant Polypyrimidine Tract Binding Protein 1 (PTBP1), LncRNA surfactant associated 1 (SFTA1P) promoted the degradation of tropomyosin 4 (TPM4) mRNA and the progression of cervical cancer." (PMID 37007117, 2023). "To investigate whether SFTA1P mediates the function of TPM4 in cervical cancer cells, we co-transfected si-SFTA1P and si-TPM4 in CaSki and C-4 I cells." (PMID 36344495, 2022). "Although there are a few studies on the biological function of TPM4 in cancers, the role of TPM4 in cervical cancer remains unclear." (PMID 36344495, 2022). "Taken together, these results imply that TPM4 may act as a tumor suppressor in cervical cancer cells." (PMID 36344495, 2022). "Our RNA-seq data showed that TPM4 is down‐regulated in cervical cancer tissues." (PMID 36344495, 2022). "To investigate the biological functions of TPM4 in cervical cancer, we detected the expression of TPM4 in cervical cancer cell lines and knocked down TPM4 using siRNAs in CaSki and C-4 I cells with relatively high basal TPM4 expression." (PMID 36344495, 2022). "Whilst previous studies have reached contradictory conclusions as to whether TPM4 acts as either an oncogene or anti-oncogene in human cancers, its role in cervical cancer remains unclear." (PMID 36344495, 2022). "Similarly, we also explored the role of PTBP1 in regulating the function of TPM4 in cervical cancer." (PMID 36344495, 2022).
hypertrophic cardiomyopathy (4 papers, 2016 to 2022). A condition in which the myocardium is hypertrophied without an obvious cause. "Interestingly, while Tpm1 is one of the main hypertrophic cardiomyopathy genes, Tpm4 is known for its inhibitory effect on actin polymerization." (PMID 36013195, 2022). "The results showed that genes (DES, MYH6, MYL2, MYL3, TPM1, TPM3, TPM4, and TTN) in MCODE 2 were significantly involved in dilated cardiomyopathy and hypertrophic cardiomyopathy (HCM)." (PMID 35645614, 2022).
dilated cardiomyopathy (3 papers, 2019 to 2022). Cardiomyopathy which is characterized by dilation and contractile dysfunction of the left and right ventricles. "The other male‐specific longevity SNP rs16981095 regulated the expression of the gene TPM4 in whole blood that its related pathways are dilated cardiomyopathy and cardiac muscle contraction." (PMID 33657282, 2021).
lung adenocarcinoma (3 papers, 2018 to 2024). A carcinoma that arises from the lung and is characterized by the presence of malignant glandular epithelial cells. "Elevated levels of TPM4, a member of the tropomyosin family of actin-binding proteins involved in cytoskeleton organization, are associated with increased cell migration and motility in lung adenocarcinoma cell lines such as A549 and NCI-H1299." (PMID 39766023, 2024). "Moreover, we collected four tissue samples of surgically removed lung adenocarcinoma and their paired normal adjacent tissue to evaluate the protein level of STOM and TPM4." (PMID 30348215, 2018).
Macrothrombocytopenia (3 papers, 2017 to 2025). "Mutation of murine Tpm4 resulted in dose-dependent macrothrombocytopenia caused by a defect in the terminal stages of platelet production." (PMID 28134622, 2017). "Collectively, these data provide convincing evidence that loss-of-function variants in TPM4 can cause macrothrombocytopenia, and suggest it plays a role in the development of the megakaryocyte lineage." (PMID 28134622, 2017). "N-Ethyl-N-nitrosourea–induced (ENU-induced) missense mutations in Tpm4 or targeted inactivation of the Tpm4 locus led to gene dosage–dependent macrothrombocytopenia in mice." (PMID 28134622, 2017). "A truncating mutation in TPM4 causes macrothrombocytopenia in humans." (PMID 28134622, 2017). "A loss-of-function allele of murine Tpm4 causes macrothrombocytopenia." (PMID 28134622, 2017). "Here, we have identified 2 unrelated families in the BRIDGE Bleeding and Platelet Disorders (BPD) collection who carry a TPM4 variant that causes truncation of the TPM4 protein and segregates with macrothrombocytopenia, a disorder characterized by low platelet count." (PMID 28134622, 2017). "TPM4 insufficiency causes macrothrombocytopenia in mice and humans in a dose-dependent manner." (PMID 28134622, 2017). "Notably, knock-out of Tpm4 causes a rare form of macrothrombocytopenia in humans and mice." (PMID 40753314, 2025). "Given that macrothrombocytopenia can be triggered by accelerated platelet clearance, we firstly examined the in vivo lifespan of Tpm4+/+, Tpm4Plt53/+, and Tpm4Plt53/Plt53 platelets." (PMID 28134622, 2017). "Mice lacking cofilin in the megakaryocyte lineage display macrothrombocytopenia, suggesting that the correct balance between TPM4 and cofilin is essential for the production of correctly sized platelets." (PMID 28134622, 2017).
Stroke (3 papers, 2014 to 2026). Sudden impairment of blood flow to a part of the brain due to occlusion or rupture of an artery to the brain. "It has been confirmed that TPM4 is the independent risk factor of stroke or heart diseases 8, while some specific tumors in human bodies may express abnormal levels of TPM4." (PMID 33390785, 2021). "Serum TPM4 levels on admission were negatively correlated with the National Institutes of Health Stroke Scale (NIHSS) score (r = -0.185, p = 0.013)." (PMID 41660075, 2026).
cardiomyopathy (2 papers, 2016 to 2022). A disease of the heart muscle or myocardium proper. "Genes in MCODE 2 (such as TPM4) were significantly involved in cardiomyopathy, and genes in MCODE 4 (such as COL4A3 and COL4A4) were involved in focal adhesion, ECM-receptor interaction, and PI3K-Akt signaling pathway." (PMID 35645614, 2022).
esophageal squamous cell carcinoma (2 papers, 2012 to 2021). Esophageal squamous cell carcinoma (ESCC) is a type of esophageal carcinoma (EC) that can affect any part of the esophagus, but is usually located in the upper or middle third. "Two papers also reported detecting tropomyosin 4- (TPM4-)ALK fusion protein expression in some cases of esophageal squamous cell carcinoma." (PMID 22852078, 2012).
gastric cancer (2 papers, 2019 to 2023). A primary or metastatic malignant neoplasm involving the stomach. "Among these selected fusion proteins, we found that the TPM4-ALK fusion protein is preferentially expressed in gastric cancer tissues compared with normal tissues." (PMID 31278140, 2019). "In a previous study, we identified the TPM4-ALK fusion gene in gastric cancer tissues of Korean patients (unpublished)." (PMID 31278140, 2019). "Previously, we identified the TPM4-ALK fusion protein in patients with gastric cancer (unpublished)." (PMID 31278140, 2019).
osteosarcoma (2 papers, 2021 to 2023). A usually aggressive malignant bone-forming mesenchymal neoplasm, predominantly affecting adolescents and young adults. "Among the top DEPs identifying fibroblastic groups from other pathological subtypes are POSTN, TPM4, RTN4, HNRNPK, and RACK1, which were directly associated with osteosarcoma progression and prognosis." (PMID 37681913, 2023). "TPM4, or Tropomyosin α-4 chain, was found to be among the differentially expressed proteins in osteosarcoma tissues compared with soft callus tissues." (PMID 37681913, 2023).
platelet disorder (2 papers, 2017 to 2018). "Since the platelet disorder associated with the TPM4 variant results in an unpredictable bleeding phenotype, these findings indicate that reduced levels of TPM4 result in a mild impairment of hemostasis." (PMID 28134622, 2017). "Together, our findings demonstrate a nonredundant role for TPM4 in platelet biogenesis in humans and mice and reveal that truncating variants in TPM4 cause a previously undescribed dominant Mendelian platelet disorder." (PMID 28134622, 2017). "Our findings demonstrate that TPM4 encodes a tropomyosin with an important nonredundant role in platelet biogenesis, and define a novel, dominant, Mendelian platelet disorder." (PMID 28134622, 2017).
Anxiety (1 paper, 2025). Intense feelings of nervousness, tension, or panic often arise in response to interpersonal stresses. "Here, we observed a heightened anxiety phenotype demonstrated in Tpm4.2−/− mice, particularly in female mice." (PMID 40753314, 2025).
atherosclerosis (1 paper, 2022). A disease characterized by the build-up of fatty material and calcium deposition in the arterial wall resulting in partial or complete occlusion of the arterial lumen. "Therefore, TPM4 may have pro-atherogenic properties, whereas coronarycalcification is strongly correlated with atherosclerosis." (PMID 39076904, 2022).
bladder cancer (1 paper, 2022). "The expression levels of TPM1, TPM2, TPM3, and TPM4 in low-grade bladder cancer were lower than those in high-grade bladder cancer." (PMID 35734544, 2022). "The expression levels of TPM1, TPM2, TPM3, and TPM4 in low grade bladder cancer were lower than those in high grade bladder cancer (P < 0.05)." (PMID 35734544, 2022). "We have previously observed that TPM1, TPM2, and TPM4 are low expressed in bladder cancer, and therefore, the infiltration of NK cell, macrophages, neutrophils, and Th1 may be reduced accordingly in bladder cancer." (PMID 35734544, 2022). "Our study showed that TPM1, TPM2, and TPM4 were underexpressed in bladder cancer tissues." (PMID 35734544, 2022). "Therefore, we infer that the low expression of TPM1, TPM2, and TPM4 is a mechanism of immunosuppression in bladder cancer." (PMID 35734544, 2022). "Therefore, the low expression of TPM1, TPM2, and TPM4 in the tumor tissues of bladder cancer may be beneficial to the rapid proliferation of bladder cancer cells, indicating the development of bladder cancer." (PMID 35734544, 2022).